UPK3B (uroplakin 3B)
Description:
Component of the asymmetric unit membrane (AUM); a highly specialized biomembrane elaborated by terminally differentiated urothelial cells. May play an important role in AUM-cytoskeleton interaction in terminally differentiated urothelial cells. It also contributes to the formation of urothelial glycocalyx which may play an important role in preventing bacterial adherence (By similarity).
Synonyms: UP3b; UPIIIb; MGC10902; p35; FLJ32198
Tractability: Antibody: UniProt places it where antibodies can reach, with high confidence; UniProt predicts a signal peptide or a membrane-spanning region; its Gene Ontology location is reachable by antibodies, with medium confidence.
Gene: Protein-coding gene on chromosome 7 (76,510,525 to 76,516,522, forward strand). Ensembl gene ENSG00000243566.
Subcellular location: Cell membrane
Gene Ontology:
Molecular function: protein binding
Cellular component: membrane; plasma membrane
Genetic constraint (gnomAD): Loss-of-function variants: 20 observed, 23.43 expected, observed/expected ratio (o/e) 0.85, 90% interval 0.6 to 1.24. The upper end of that interval is the gene's LOEUF score, 1.24, which puts it in group 5 of 6, group 1 being the genes least tolerant of losing a copy. Missense variants: 295 observed, 311.22 expected, observed/expected ratio (o/e) 0.95, 90% interval 0.86 to 1.04. Synonymous variants: 136 observed, 133.07 expected, observed/expected ratio (o/e) 1.02, 90% interval 0.89 to 1.18.
Homologues: Orthologues: macaque UPK3B (93% identical), dog UPK3B (79% identical), mouse Upk3b (78% identical), pig UPK3B (78% identical), rat Upk3b (77% identical), rabbit UPK3B (73% identical), guinea pig UPK3B (72% identical), tropical clawed frog upk3b (32% identical), zebrafish upk3b (22% identical). Paralogues in human: UPK3BL1 (37% identical), UPK3BL2 (37% identical), UPK3A (28% identical).
Diseases named in the same sentence as UPK3B in open-access papers:
UPK3B is named in the same sentence as 33 diseases in open-access papers, as found by Europe PMC text mining. Sharing a sentence is not in itself a finding about the gene and the disease. The quoted sentences say what the papers report.
colon cancer (3 papers, 2022 to 2024). "Immunohistochemical methods were used to compare the expression of PRGs (SLC2A3, TMPRSS11E, and UPK3b) in colon cancer and their expression in normal gastric tissues." (PMID 36246625, 2022). "In a recent study, functional analysis revealed a negative correlation between three genes (SLC2A3, TMPRSS11E, and UPK3B) can predict the overall survival of patients with colon cancer, finding that it is negatively correlated with the proliferation and migration of colon cancer cells." (PMID 39062587, 2024). "In the present study, a four-gene signature of colon cancer, consisting of HSF4, UPK3B, ZNF767P, and AGAP9, was generated and validated." (PMID 36681801, 2023).
mesothelioma (3 papers, 2011 to 2022). A usually malignant and aggressive neoplasm of the mesothelium which is often associated with exposure to asbestos. "In summary, Upk3b immunohistochemistry is a useful diagnostic tool for the distinction of mesotheliomas from other thoracic tumors and the visualization of normal mesothelial and umbrella cells." (PMID 36292206, 2022). "The expression pattern of Upk3b in normal and neoplastic tissues offers potential diagnostic applications of Upk3b IHC, including the distinction of mesotheliomas from other primary or metastatic thoracic tumors as well as the visualization of normal mesothelial and umbrella cells." (PMID 36292206, 2022). "We go on to demonstrate that polyclonal antibodies against two of these, LRRN4 and UPK3B react with human mesothelioma tissue localised to the plasma membrane." (PMID 21984916, 2011). "Upk3b expression was most frequent in mesotheliomas (82.1% of epithelioid and 30.8% of biphasic) and in urothelial tumors of the urinary bladder, where the positivity rate decreased from 61.9% in pTaG2 (low grade) to 58.0% in pTaG3 (high grade) and 14.6% in pT2-4 cancers." (PMID 36292206, 2022). "To confirm the specificity of these markers in human mesothelium and mesothelioma we designed primers against human MSLN, UPK3B, NKAIN4 and LRRN4 and tested their specificity by qRTPCR against a panel of 45 human total RNAs." (PMID 21984916, 2011). "Despite this, testing the cell line panel revealed that MSLN still appears to be a better marker of mesothelioma than LRRN4 and UPK3B." (PMID 21984916, 2011). "Interestingly MSLN levels appear to be upregulated in the mesothelioma lines compared to the primary mesothelial cells, while LRRN4 and UPK3B, are either lost or down-regulated." (PMID 21984916, 2011). "In addition, UPK3B and MSLN are significantly positively correlated with mesothelioma E-score." (PMID 36467966, 2022).
bladder cancer (2 papers, 2012 to 2023). "Increased UPK3B expression, decreased E-calcineurin expression, and increased cell proliferation have been observed in FOXA1-deficient RT4 bladder cancer cells, demonstrating a strong relationship between high UPK3B expression and tumor malignancy." (PMID 36681801, 2023).
lung carcinoma (2 papers, 2011 to 2023). "To investigate changes of PMCs, we evaluated the transcriptomes of PMCs (CALB1, WT1, and UPK3B-positive cells) in pleural effusion from patients with congestive heart failure or patients with lung cancer." (PMID 37649596, 2023).
cardiac hypertrophy (1 paper, 2023). "Cluster 14 (Upk3b) was a specific cluster expressing mesothelial cells markers, suggesting a minor role of transition between mesothelial cell and fibroblasts in cardiac hypertrophy development." (PMID 36805782, 2023).
Hypertension (1 paper, 2017). The presence of chronic increased pressure in the systemic arterial system. "Three genes within the chromosome 12 congenic strain interval (Dtx2, Upk3b, Upk3bl) contain SNVs that were significantly associated across 42 rat strains with both hypertension and insulin resistance." (PMID 28130354, 2017). "SNVs in Dtx2, Upk3b and Upk3bl were found to be significantly associated with both insulin resistance and hypertension." (PMID 28130354, 2017).
liver fibrosis (1 paper, 2023). "Transcriptome analysis of liver fibrosis has identified UPK3B as a potential regulator of hepatic stellate cell (HSC) activation-induced liver fibrosis." (PMID 36681801, 2023).
macular degeneration (1 paper, 2025). Loss of vision in the central portion of the retina (macula), secondary to retinal degeneration. "Novel structural target genes including Ermn and Upk3b, along with macular degeneration and inherited retinal disease genes were identified as downregulated, and a strong upregulation of TGFß/BMP signaling and effectors was observed." (PMID 40233131, 2025).
malignant mesothelioma (1 paper, 2022). A malignant neoplasm of the pleura or peritoneum, arising from mesothelial cells. "Irrespective of the origin and role of Upk3b positive ovarian cancer cells, their occurrence is a limitation for using Upk3b IHC for diagnosing malignant mesothelioma of the peritoneum." (PMID 36292206, 2022).
Obesity (1 paper, 2019). Accumulation of substantial excess body fat. "Genes functionally non-reported in adipose tissue showed a link with a GWAS obesity trait (SLC19A3 and UPK3B genes) and a GWAS blood lipids trait (LVRN, CD300LG, and HAS1 genes)." (PMID 30816281, 2019).
ovarian carcinoma (1 paper, 2022). A malignant neoplasm originating from the surface ovarian epithelium. "It is of note that Upk3b positivity was often strong in ovarian cancer cells but usually involved rather small subsets of cells which resulted in a staining classification of “weak” or “moderate” positivity according to our predefined criteria." (PMID 36292206, 2022). "Less commonly, Upk3b expression was also seen in Brenner tumors of the ovary (10.8%), as well as in four other subtypes of ovarian cancer (0.9–10.6%)." (PMID 36292206, 2022). "The relatively high rate of Upk3b positivity in ovarian carcinomas may be reflective of the close morphological and functional similarity of ovarian surface epithelium (also referred to as “ovarian mesothelium”) and mesothelial cells which regularly express Upk3b." (PMID 36292206, 2022).
papillary carcinoma (1 paper, 2022). A malignant epithelial neoplasm characterized by a papillary growth pattern. "High positivity rates of >60% were only seen in non-invasive papillary carcinomas while almost 80% of the muscle-invasive cancers which are causing most diagnostic difficulties were Upk3b negative." (PMID 36292206, 2022).
papillary urothelial neoplasm (1 paper, 2022). "As such, Upk3b IHC emerges as a suitable tool to selectively visualize the umbrella cell layer, the integrity of which has been suggested as a criterion for the grading and classification of papillary urothelial neoplasms." (PMID 36292206, 2022).
type 2 diabetes (1 paper, 2021). "UPK3B is regarded as a mesothelial-like cell marker of a major adipocyte progenitor cell subpopulations which may induce adipocyte dysfunction in visceral adipose tissue in type 2 diabetes." (PMID 34295899, 2021).
urothelial carcinoma (1 paper, 2022). A malignant neoplasm derived from the transitional epithelium of the urinary tract (urinary bladder, ureter, urethra, or renal pelvis). "The fraction of Upk3b positive cases further decreased to 14.6% in muscle invasive urothelial carcinomas (p < 0.0001)." (PMID 36292206, 2022). "Among pT2-4 urothelial carcinomas, Upk3b staining was unrelated to tumor stage, lymph node status, and patient prognosis." (PMID 36292206, 2022).
urothelial neoplasm (1 paper, 2022). A neoplasm involving a urothelium. "Although urothelial neoplasms comprise 68.7% of all Upk3b positive cases in our study, the utility of Upk3b for the distinction of urothelial cancer from other neoplasms may be limited." (PMID 36292206, 2022). "Due to of the limitation of Upk3b immunostaining to umbrella cells in normal urothelium, Upk3b positivity of urothelial neoplasms is mostly driven by Upk3b expressing remnants of the umbrella cell layer which are predominantly observed in low grade non-invasive papillary carcinomas." (PMID 36292206, 2022).
tumor (7 papers, 2011 to 2023). "Inevitably, the protein expression levels of these two high-risk genes (SLC2A3 and UPK3b) were significantly increased in tumor samples, with more obvious antibody staining and higher percentage of stained tissues." (PMID 36246625, 2022). "Our tumor analysis identified Upk3b expression in only 17 of 151 analyzed cancer categories and enabled the definition of a ranking order of tumor types according to their UpK3b positivity rate which essentially paralleled the findings in normal tissues." (PMID 36292206, 2022). "Based on RNA expression studies, Upk3b is expressed in a limited number of normal and tumor tissues." (PMID 36292206, 2022). "The potential use of Upk3b as a diagnostic or prognostic marker in tumor diagnosis has not yet been extensively investigated." (PMID 36292206, 2022). "Four additional tumor entities showed a weak to moderate Upk3b positivity in less than 5% of cases." (PMID 36292206, 2022). "In tumor tissues, Upk3b was detectable in only 17 of 151 (11.3%) of tumor types." (PMID 36292206, 2022). "Results showed that some of the proteins found in EVs were shared among these cancer types, while others were tumour‐specific, and with respect to UC, the EVs expressed high levels of UPK1A, UPK1B, UPK2 and UPK3B." (PMID 35838333, 2022). "In this study, we therefore analyzed a preexisting set of tissue microarrays (TMAs) containing more than 17,000 tumor tissue samples from 151 different tumor types and subtypes, as well as 76 non-neoplastic tissue categories for Upk3b expression by IHC." (PMID 36292206, 2022).
cancer (3 papers, 2011 to 2022). A tumor composed of atypical neoplastic, often pleomorphic cells that invade other tissues. "Therefore, Upk3b IHC, which should label all normal mesothelial cells, might facilitate cancer cell detection in diagnostic cytology." (PMID 36292206, 2022). "In the case of LRRN4 and UPK3B the expression was only detected in 8 or 6 of the tested lines suggesting these markers are down-regulated or lost in cancer." (PMID 21984916, 2011). "Data on a potential role of Upk3b in cancer are so far solely derived from RNA screening studies." (PMID 36292206, 2022). "Based on our data, it might be speculated that Upk3b expression might potentially distinguish these subtypes and predominantly occur in cancers derived from the ovarian surface epithelium." (PMID 36292206, 2022). "Studies analyzing Upk3b protein expression in cancer by immunohistochemistry (IHC) are so far lacking." (PMID 36292206, 2022). "However, scattered Upk3b positive cells morphologically always resembled typical cancer cells and not mesothelial cells in our tumors." (PMID 36292206, 2022).
infection (1 paper, 2025). The state of being infected such as from the introduction of a foreign agent such as serum, vaccine, antigenic substance or organism. "AAV1-Cre-GFP injection led to a high infection efficiency in the peritoneal mesothelial layer, as indicated by the colocalization of UPK3B and GFP in the peritoneum." (PMID 41320784, 2025).
UPK3B also shares sentences with these, for which no sentence is quoted: breast carcinoma (2 papers); epithelioid mesotheliomas (2); adenocarcinoma (1); atherosclerosis (1); cervical cancer (1); colon adenocarcinoma (1); congestive heart failure (1); Insulin resistance (1); pancreatic adenocarcinoma (1); Pleural effusion (1); prostate carcinoma (1); retinal disease (1); thoracic tumors (1); tumors of the ovary (1).